TLR1 (toll like receptor 1)
Diseases named in the same sentence as TLR1 in open-access papers (continued):
Sharing a sentence is not in itself a finding about the gene and the disease.
asthma (26 papers, 2005 to 2025). "In particular, TLR-1 SNP rs5743618 has been associated with increased asthma prevalence during the first six years of life if bronchiolitis had been contracted within the first six years of life." (PMID 36362786, 2022). "In the meta‐analysis of GWASs that have been performed on both children and adult populations with self‐reported allergy, the found shared susceptibility loci with asthma included (rs2101521, A‐> G) chromosome 4p14 near TLR1, TLR6 and TLR10." (PMID 33133517, 2020). "In the meta‐analysis of GWASs of children and adults with asthma and hay fever, and controls, TLR1 (rs4833095, T) was associated with the risk of asthma with co‐existing hay fever." (PMID 33133517, 2020). "Several TLR1, 2, and 6 polymorphisms have been described with functional and genetic association studies including asthma, rheumatoid arthritis, and inflammatory bowel disease." (PMID 28912808, 2017). "The elevated expression of TLR4 and TLR1/TLR2 induced by type-2 cytokines is assumed to modulate the impact of bacterial infections on Th2 associated pulmonary diseases like asthma." (PMID 16316467, 2005). "Furthermore, TLR1 SNPs, including the missense variants, have been associated with asthma or allergy and lymphocyte counts and examined in infectious traits, including Lyme disease." (PMID 38503741, 2024). "Furthermore, the polymorphism of the TLR1 gene is associated with the risk of asthma." (PMID 40672946, 2025). "The expression of TLR1 on peripheral blood mononuclear cells is significantly higher in patients with asthma than that in healthy individuals, indicating that TLR1 plays a role in the pathogenesis of asthma." (PMID 40672946, 2025). "We have previously studied the TLR1 rs5743618, TLR2 rs5743708, and TLR6 rs5743810 polymorphisms and reported their associations with post-bronchiolitis asthma at preschool age10." (PMID 28592890, 2017). "TLR1, TLR2, TLR6, and TLR10 comprise the TLR2 subfamily, and TLR1, TLR2, TLR6, and TLR10 gene polymorphisms seem to play a role in susceptibility to asthma, atopic eczema, and allergic rhinitis." (PMID 28592890, 2017). "Despite some limitations of the study, our data point to a potentially protective effect of Tlr1/2 mRNA treatment on HDM induced asthma." (PMID 27101288, 2016). "Genetic variations in TLR1, TLR2, TLR4, TLR6 and TLR10 have been associated with the development of asthma." (PMID 24524443, 2014). "As PRRs in the lung can modulate ongoing chronic inflammation during asthma, the mRNA expression of Tlr1-9 and Nod1-2 were measured." (PMID 24735374, 2014). "In severe asthma, allergen challenge only increased the expression of Tlr2 and allergen sensitization and challenge significantly increased Tlr1 expression when compared to sensitized only mice." (PMID 23781124, 2013). "As PRRs in the lung can modulate ongoing chronic inflammation during asthma, the mRNA expression of Tlr1-13 and Nod1 and 2 was measured." (PMID 23781124, 2013). "These seemingly contradictory findings suggest that the specific role of TLR1 in asthma may be regulated by multiple factors, and it is worthy of further in-depth exploration." (PMID 40672946, 2025). "Specifically, the strongest remaining signal (P < 10−15) after using ACs surrounds rs5743618 on chromosome 4, linked to toll-like-receptor genes involved in innate immunity, including TLR1 and TLR10, one of the strongest hay fever hits in European GWAS cohorts, with weaker asthma risk association." (PMID 39901012, 2025). "However, TLR1/2 mRNA treatment has demonstrated protective effects on asthma induced by house dust mites in mice." (PMID 40672946, 2025). "For instance, some studies with TLR1 or TLR2 agonists suggested that their activation results in asthma inhibition, while other studies indicated that activation of these receptors could promote allergic asthma." (PMID 29867994, 2018).
asthma (continued). "Therefore, we investigated the effect of a preventative treatment with combinations of Tlr1, Tlr2 and Tlr6 mRNA in a House Dust Mite-induced mouse model of asthma." (PMID 27101288, 2016). "Individuals with asthma have an increased expression of TLR1 and TLR10 in their airway epithelial cells compared to controls, suggesting these genes are asthma therapeutic targets." (PMID 39406500, 2024). "TWAS genes of known biological interest in asthma include IL1RL1 on 2q12, TLR1 on 4p14, TSLP on 5q22, SMAD3 on 15q22-q23, and IL4R on 16p12." (PMID 34103634, 2021). "Of the upregulated genes, NTS, TLR1, and MPO mRNA was only detectable in the asthma samples, whilst of the downregulated genes, IL7R and PDE4R mRNA were only observed in the control samples." (PMID 31221987, 2019). "Only two children (8%) with wild genotypes in the TLR1, TLR2 and TLR6 genes had asthma during the first six years of life, compared to 30% in those with variant genotypes." (PMID 26741133, 2016). "Here, based on the data of asthma-protecting TLR-haplotypes, we investigated the intratracheal application of combinations of chemically modified Tlr1, Tlr2 and Tlr6 mRNA in a House Dust Mite (HDM)-induced mouse model of asthma." (PMID 27101288, 2016). "To investigate the role of TLRs in asthma development, we constructed AIPI model by using ovalbumin (OVA) to sensitize and challenge E3 rats and detected TLR1-9 mRNA expression in spleen, mLN and lung of the rats by using quantitative real-time polymerase chain reaction (PCR)." (PMID 21364926, 2011).
tuberculosis (24 papers, 2007 to 2023). A chronic, recurrent infection caused by the bacterium Mycobacterium tuberculosis. "The heterozygous genotype (AG) of the TLR1 743 A > G polymorphism is predominant in all tuberculosis cases, including PTB (49%), MDR-TB (48%), and XDR-TB cases (46%) and healthy controls (57%)." (PMID 38481606, 2023). "TLR1 polymorphism is associated with the susceptibility of multiple diseases, including tuberculosis, pancolitis and prostate cancer." (PMID 30577800, 2018). "In conclusion, SNP rs5743565 C allele and rs5743557 A allele within TLR1 gene were significantly associated with the reduced risk for tuberculosis in Western Chinese population." (PMID 29416723, 2018). "The relationship between TLR1 gene polymorphism and the incidence of tuberculosis is also associated with other SNPs or other biological mechanisms." (PMID 29416723, 2018). "TLR2 and TLR1 act together to mediate responses to M. tuberculosis and the role of TLR1/2 gene variants in the predisposition to tuberculosis has been investigated." (PMID 25312698, 2015). "Though this study found that rs5743565 and rs5743557 reduce the risk of tuberculosis in western China population, these two SNPs could only partially explain why TLR1 affects the pathogenesis of tuberculosis." (PMID 29416723, 2018). "Rs5743565 and rs5743557 in the TLR1 gene may contribute to decreased risk for tuberculosis susceptibility in a Western Chinese population." (PMID 29416723, 2018). "TLR1 I602S also has been shown to influence risk of tuberculosis." (PMID 22529866, 2012). "The association of this chromosomal location with the susceptibility to bacterial infections in cattle (clinical mastitis) and mice (Listeria moncytogenes) is consistent with the function of TLR1 and 6 and polymorphisms within these genes have been associated with tuberculosis and malaria in humans." (PMID 19432955, 2009). "After adjustment for tuberculosis status, the rs4986790-G (TLR4) and rs5743551-G (TLR1) alleles were significantly associated with the changes in CD4+ cell count above/below 200 cells/mm3." (PMID 37606452, 2023). "Compared to control subjects, African American tuberculosis cases had a significantly increased frequency of rare NSPs in TLR1 (OR = 3.32; P = 0.002), TLR6 (OR = 1.85; P = 0.040), and TLR10 (OR = 1.76; P = 0.009)." (PMID 18091991, 2007). "This may be the first study to analyze the immune response to drug-resistant tuberculosis patients by analyzing TLR2 (−196 to −174) del and TLR1 743 A > G gene polymorphism." (PMID 38481606, 2023). "Therefore, on condition that we intend to interpret the role of TLR1 in the pathogenesis of tuberculosis accurately, we should understand the changes of more SNPs comprehensively." (PMID 29416723, 2018). "The TLR1 genotypes 743AA/1805GG (TLR1neg) are associated with a TLR1 negative phenotype, impaired function and susceptibility to tuberculosis." (PMID 23391127, 2013). "The objective of this study is to analyze the association between TLR2 deletion (−196 to −174) and TLR1 743 A > G gene polymorphism with drug resistant tuberculosis (PTB, MDR-TB, and XDR-TB) in a population from Agra, Uttar Pradesh." (PMID 38481606, 2023). "Further studies with larger numbers of old and young individuals will finally define whether a specific TLR1 genotype contributes to larger lifespan or susceptibility to tuberculosis or not." (PMID 23391127, 2013). "TLR polymorphism with a significant association with pulmonary tuberculosis was present in TLR1 rs5743572 in intron, TLR2 rs3804100 in exon, and TLR6 rs5743808 in exon and among MDR-TB isolates from patients with pulmonary MDR-TB of a severe and moderate/mild degree." (PMID 36611413, 2022). "The table summarizes the mean percentages of inflammatory cells expressing TLR1, TLR2, TLR4, TLR7, and TLR9 in LNs from patients with AOSD, tuberculosis (Tb) lymphadenitis, T cell lymphoma, histiocytic necrotizing lymphadenitis (HNL), and reactive LNs." (PMID 35715478, 2022).
tuberculosis (continued). "A previous study reported that TLR1 regulates polypeptide-induced signaling and responds to extracts of M. tuberculosis, suggesting that TLR1 may substantially regulate the immune response against the bacillus and impact on the outcome of TB." (PMID 29988507, 2018). "Activation of Toll-like receptor 1 (TLR1) and TLR2 by tuberculosis enhances 1α-hydroxylase expression, the enzyme mediates the synthesis of 1,25(OH)2D3, production of antimicrobial peptide cathelicidin, and induction of tolerogenic DCs and T cells." (PMID 23519108, 2013). "In support of this hypothesis, the TLRs are upregulated as a group in both melioidosis (TLR1, TLR2, TLR4, TLR5, TLR6, TLR8 and TLR10) and tuberculosis (TLR2, TLR4, TLR5, TLR6, TLR7, TLR8)." (PMID 23383015, 2013). "In another study, also in an Ethiopian cohort of HIV co-infected TB patients, 7 genes (FCGR1A, RAB24, TLR1, TLR4, MMP9, NLRC4, and IL1B) accurately discriminated between active tuberculosis disease and latent infection." (PMID 33692804, 2021). "In a recent study, an increased expression of TLR-1, TLR-2, TLR-4 and TLR-6 has been reported at the mRNA level in peripheral blood mononuclear cells, but not in broncho-alveolar lavage cells from patients with tuberculosis compared to healthy controls." (PMID 20718957, 2010).
Sepsis (21 papers, 2007 to 2025). Sepsis is defined as life-threatening organ dysfunction caused by a dysregulated host response to infection. "The rs5743810 polymorphism in the TLR6 gene is closely related to the rs5743551 polymorphism in the TLR1 gene, which has been shown to be closely related to the severity of pneumonia and sepsis." (PMID 36611413, 2022). "In North American patients, TLR1 variants are associated with outcomes in sepsis, including survival." (PMID 30866782, 2019). "Next, strong, moderate, and weak levels of evidence of a significant association with sepsis risk were assigned to 4 (TLR1 rs5743551-7202A/G, RAGE rs1800625-429 T/C and rs1800624-374 T/A, and miR-608 rs4919510G/C), 14, and 11 variants, respectively." (PMID 30683156, 2019). "Genotypes carrying the T (major) allele of TLR1 rs5743551—an allele associated with improved outcomes in sepsis—were associated with higher parasitaemia measured on day zero (p = 0.03)." (PMID 26738805, 2016). "In white North Americans, common functional genetic variation in TLR1 is associated with organ failure and death from sepsis." (PMID 24392083, 2014). "Three TLR1 variants have been described as associated with sepsis, although the relationship is complex." (PMID 24392083, 2014). "The allele frequency of these TLR1 variants is markedly different around the world, potentially leading to differential associations with outcomes from sepsis." (PMID 24392083, 2014). "We additionally explored the relationship of TLR1 polymorphisms and of particular haplotypes with serum levels of four biomarkers of inflammation taken at three stages of sepsis development." (PMID 21048935, 2010). "Seven tagging single nucleotide polymorphisms of the TLR1 gene were genotyped in samples from a prospective multicenter case-only study of patients with severe sepsis admitted into a network of intensive care units followed for disease severity." (PMID 21048935, 2010). "Recently, TLR1 gene polymorphisms have been found correlated with whole blood hyper-inflammatory responses to pathogen-associated molecules and associated with sepsis-associated multiorgan dysfunction and acute lung injury (ALI)." (PMID 21048935, 2010). "We examined the association of common variants of TLR1 gene with sepsis-derived complications in an independent study and with serum levels for four inflammatory biomarkers among septic patients." (PMID 21048935, 2010). "For example, rs4957796 within the FER gene and rs5743551 located into the promoter region of TLR1 might affect the risk of sepsis." (PMID 33281864, 2020). "As the rs76600635 variant has not been previously associated with outcomes in sepsis, additional studies of this TLR1 variant and its potential mechanistic role in the host immune response to melioidosis and other causes of sepsis in East Asian subjects are required." (PMID 30866782, 2019). "Since malaria exerts strong genetic pressure on the human genome, protection from parasitaemia associated with TLR1 rs5743551 may account for the maintenance of an allele associated with poor outcomes in Caucasians with sepsis." (PMID 26738805, 2016). "Association p-values of TLR1 tSNPs with severe sepsis complications." (PMID 21048935, 2010). "Given the association of TLR1 1805G with Th1-mediated immune events, this SNP may influence the pathogenesis of any number of inflammatory conditions, including chronic mycobacterial infection, autoimmune disorders, sepsis and allergic reactions." (PMID 18461142, 2008). "In this setting, previous genetic studies on several gain of function SNPs in genes of receptors and signaling molecules upstream of NF-κB, such as TLR1 and IRAK1, showed a significant association with severity of sepsis." (PMID 27059500, 2016). "Our findings highlight the need for additional studies of TLR1 and other innate immune genetic modulators of the inflammatory host response and determinants of sepsis in southeast Asian populations." (PMID 24392083, 2014).
Sepsis (continued). "Only relatively recently, however, has TLR1 been carefully studied as an important regulator of the host response in sepsis, particularly in human disease." (PMID 24392083, 2014). "TLR2 forms heterodimers with either TLR1 or TLR6 and polymorphisms in these receptors have been associated with atopic asthma and organ dysfunction in sepsis." (PMID 21124967, 2010). "Prior studies evaluating TLR1 variants associated with sepsis outcomes in North American populations have not extended to Thai populations with melioidosis." (PMID 30866782, 2019). "Our study of genetic variation in Thais with melioidosis offers an opportunity to examine the association of common TLR1 variants with clinical outcome from one of the major Gram-negative causes of sepsis in northeast Thailand." (PMID 24392083, 2014). "We speculate that uncharacterized functional TLR1 genetic variation in Asians remains to be discovered, and that this may regulate outcomes in sepsis." (PMID 24392083, 2014). "While melioidosis is representative of Gram-negative sepsis, a prior study of TLR1 polymorphisms in sepsis noted a relationship (in several cohorts) between frequency of Gram-positive infection and rs5743551 genotype." (PMID 24392083, 2014). "There is evidence that TLR1 and TLR6-receptors are not redundant, since the TLR1-7202G mutation is associated with higher mortality rates in sepsis and hyperresponsiveness towards Pam3Cys." (PMID 21124967, 2010). "The global diversity in TLR1 genetic architecture may play a role in the response to sepsis." (PMID 30866782, 2019). "Given the different distribution of TLR1 alleles in Asia, it is not clear what the associations of these variants may be with outcomes from sepsis in a southeast Asian population." (PMID 24392083, 2014). "Congruently, risk alleles associated with increased nuclear factor κB (NF-κB) activation upon TLR1 stimulation in previous studies, were related with reduced interleukin-10 and elevated C-reactive protein serum levels during the first week of sepsis development." (PMID 21048935, 2010). "Candidate gene studies for traumatic patients identified several SNPs in lipopolysaccharide-binding protein (LBP), toll-like receptor 1(TLR1), and tumor necrosis factor-alpha (TNF-α) which were related to the development of sepsis." (PMID 30479651, 2018). "Interestingly, Toll‐like receptor signalling was detected in sepsis, specifically in the brain (prefrontal cortex and hippocampus), via the upregulation of genes such as CD14, TLR1, TLR2, TLR3, TLR7, IRAK3 and IRAK4." (PMID 37731199, 2023). "This study helps us to understand the specific mechanism of the signalling transduction of TLR2/2, TLR2/1 and TLR2/6, and it may provide us with novel clues to design targeted therapeutics against TLR2/2-, TLR1/2- and TLR2/6-induced sepsis." (PMID 23626692, 2013). "To determine the effect of B. pseudomallei sepsis on TLR protein expression at the surface of peripheral blood cells, we compared the expression of CD14, TLR1, TLR2, and TLR4 on circulating monocytes and granulocytes of patients with melioidosis and healthy controls using FACS analysis." (PMID 17676990, 2007).